HAO2 (hydroxyacid oxidase 2)
Description:
Oxidase that catalyzes the oxidation of medium and long chain hydroxyacids such as 2-hydroxyhexadecanoate and 2-hydroxyoctanoate, to the corresponding 2-oxoacids. Its role in the oxidation of 2-hydroxy fatty acids may contribute to the general pathway of fatty acid alpha-oxidation (Probable). Active in vitro with the artificial electron acceptor 2,6-dichlorophenolindophenol (DCIP), but O2 is believed to be the physiological electron acceptor, leading to the production of H2O2. Is not active on glycolate, glyoxylate, L-lactate and 2-hydroxybutanoate.
Synonyms: HAOX2; GIG16
Tractability: Small molecule: it belongs to a druggable protein family. PROTAC: its protein half-life has been measured; a small molecule that binds it is known.
Target class: Enzyme; Oxidoreductase
Gene: Protein-coding gene on chromosome 1 (119,368,727 to 119,394,258, forward strand). Ensembl gene ENSG00000116882.
Subcellular location: Peroxisome
Subcellular location (Human Protein Atlas): Cytosol; Vesicles
Pathways (Reactome):
Metabolism: Peroxisomal lipid metabolism
Protein localization: Peroxisomal protein import
Gene Ontology:
Molecular function: (S)-2-hydroxy-acid oxidase activity; protein binding; FMN binding; oxidoreductase activity
Biological process: fatty acid oxidation; fatty acid metabolic process
Cellular component: peroxisomal matrix; peroxisome; cytosol
Genetic constraint (gnomAD): Loss-of-function variants: 29 observed, 29.73 expected, observed/expected ratio (o/e) 0.98, 90% interval 0.73 to 1.33. The upper end of that interval is the gene's LOEUF score, 1.33, which puts it in group 5 of 6, group 1 being the genes least tolerant of losing a copy. Missense variants: 377 observed, 358.35 expected, observed/expected ratio (o/e) 1.05, 90% interval 0.97 to 1.15. Synonymous variants: 146 observed, 142.31 expected, observed/expected ratio (o/e) 1.03, 90% interval 0.9 to 1.18.
Homologues: Orthologues: chimpanzee HAO2 (99% identical), macaque HAO2 (98% identical), pig HAO2 (83% identical), dog HAO2 (82% identical), rabbit HAO2 (81% identical), rat Hao2 (74% identical), mouse Hao2 (71% identical), tropical clawed frog hao2 (63% identical), zebrafish hao2 (61% identical), Drosophila melanogaster Hao (47% identical), Caenorhabditis elegans F41E6.5 (43% identical). Paralogues in human: HAO1 (47% identical), CARNS1 (23% identical).
Diseases named in the same sentence as HAO2 in open-access papers:
HAO2 is named in the same sentence as 15 diseases in open-access papers, as found by Europe PMC text mining. Sharing a sentence is not in itself a finding about the gene and the disease. The quoted sentences say what the papers report.
atopic dermatitis (1 paper, 2018). "Some of lipid metabolic genes discovered in our analysis were also reported as declined genes in patients with psoriatic (ACSBG1, ALOX15B, ELOVL3, FADS1, FADS2, and THRSP) or atopic dermatitis (CYP4F8, ELOVL3, FADS1, FADS2, FAR2, and HAO2)." (PMID 30021930, 2018).
clear cell renal carcinoma (1 paper, 2022). A malignant epithelial neoplasm of the kidney characterized by the presence of lipid-containing clear cells within a vascular network. "We identified five survival-related genes (AGR2, HAO2, IGF2BP1, MCCD1 and OLFM4) in clear cell renal carcinoma patients." (PMID 36516496, 2022).
kidney tumors (1 paper, 2022). "Overexpression of HAO2 has also been shown to enhance cellular reactive oxygen species, stimulate lipid oxidation in tumor cells, and limit the formation of liver and kidney tumors; however, the molecular mechanism is unknown." (PMID 35528616, 2022).
lung adenocarcinoma (1 paper, 2024). A carcinoma that arises from the lung and is characterized by the presence of malignant glandular epithelial cells. "TCGA and GTEx database results showed significant differences in the expression of enzymes and transporters related to oxalate metabolism (LDHA, GRHPR, AGT, DAO, HAO2 and SLC26A1) in tumor tissues of lung adenocarcinoma patients." (PMID 38567154, 2024).
lupus (1 paper, 2023). "In this study, we subjected the autoimmune-prone MRL mice to BaP exposure before lupus onset and found that the kidneys were a major organ directly affected by the metabolism of benzene-containing compounds, with the increased expression of BaP-target genes including Cyp4b1 and Hao2." (PMID 37047136, 2023).
tumor (6 papers, 2020 to 2025). "Subsequent univariate Cox and LASSO regression analyses narrowed the selection to five key genes—GGT6, HAO2, SLPI, MELK, and EIF4A1—whose expression patterns correlated strongly with tumor grade, clinical stage, and metastatic status." (PMID 40709174, 2025). "ADH5, NUDT7, PTGES3, D2HGDH, HAO2 and CPT1C also play regulatory roles in the pathological processes of various tumours." (PMID 36643625, 2023). "Meanwhile, RT-qPCR assays revealed that ALDH6A1, FBP1, HAO2 and PSAT1 were markedly under-expressed in tumor tissues in exceeding 60% cases, and that TYMP, HK3, P4HA3, IL4I1, CYP26A1 and CPT1B were over-expressed in tumor tissues in exceeding 70% cases." (PMID 32737333, 2020).
cancer (3 papers, 2019 to 2022). A tumor composed of atypical neoplastic, often pleomorphic cells that invade other tissues. "The 13 overexpressed genes were reported to play a role in RCC: PAX2, NAT8, GBA3, SLC22A2 other cancer types: AOC1, HAO2, TMEM27, cell death (NPR3) or kidney metabolism: TMEM171, CYS1." (PMID 31150395, 2019). "KLHL6, HAO2, and OSR2 have been shown to be involved in the prognosis of other cancers." (PMID 36185403, 2022).
HAO2 also shares sentences with these, for which no sentence is quoted: hepatocellular carcinoma (3 papers); Alzheimer disease (1); cardiovascular disease (1); cholestasis (1); colitis (1); diabetes mellitus (1); Hypertension (1); infection (1).